IL7R (interleukin 7 receptor)
Description:
Receptor for interleukin-7. Also acts as a receptor for thymic stromal lymphopoietin (TSLP).
Synonyms: IL-7R-alpha; CD127; IL7RA; lnc-IL7R; IL-7Ralpha; IL7Ralpha; sIL-7R; CDw127; ILRA; IMD104
Tractability: Antibody: its Gene Ontology location is reachable by antibodies, with high confidence; UniProt places it where antibodies can reach, with medium confidence; UniProt predicts a signal peptide or a membrane-spanning region; the Human Protein Atlas places it where antibodies can reach. PROTAC: UniProt records ubiquitination sites on it; ubiquitination databases record sites on it.
Gene: Protein-coding gene on chromosome 5 (35,852,695 to 35,879,603, forward strand). Ensembl gene ENSG00000168685.
Subcellular location: Cell membrane (Isoform 1); Cell membrane (Isoform 3); Secreted (Isoform 4)
Subcellular location (Human Protein Atlas): Plasma membrane
Pathways (Reactome):
Vesicle-mediated transport: Cargo recognition for clathrin-mediated endocytosis; Clathrin-mediated endocytosis
Immune System: Interleukin-7 signaling
Gene Ontology:
Molecular function: cytokine receptor activity; interleukin-7 receptor activity; protein binding; antigen binding
Biological process: cellular homeostasis; interleukin-7-mediated signaling pathway; positive regulation of cell population proliferation; positive regulation of receptor signaling pathway via STAT; cell surface receptor signaling pathway; hemopoiesis; immune response; positive regulation of receptor signaling pathway via JAK-STAT; regulation of DNA recombination; signal transduction; cytokine-mediated signaling pathway; defense response to Gram-positive bacterium
Cellular component: plasma membrane; clathrin-coated endocytic vesicle membrane; external side of plasma membrane; extracellular region; membrane
Genetic constraint (gnomAD): Loss-of-function variants: 31 observed, 42.64 expected, observed/expected ratio (o/e) 0.73, 90% interval 0.55 to 0.98. The upper end of that interval is the gene's LOEUF score, 0.98, which puts it in group 4 of 6, group 1 being the genes least tolerant of losing a copy. Missense variants: 582 observed, 509.73 expected, observed/expected ratio (o/e) 1.14, 90% interval 1.07 to 1.22. Synonymous variants: 207 observed, 194.79 expected, observed/expected ratio (o/e) 1.06, 90% interval 0.95 to 1.19.
Gene-disease validity (ClinGen):
ClinGen rates the evidence that IL7R causes each of these diseases.
immunodeficiency 104 (autosomal recessive): Definitive. A severe combined immunodeficiency characterized by being T cell-negative, B cell-positive and natural killer cell-positive and that has material basis in homozygous or compound heterozygous mutation in the IL7R gene on chromosome 5p13 or the CD45 gene on chromosome 1q31.
Cancer hallmarks: proliferative signalling (promotes); escaping programmed cell death (promotes); tumour promoting inflammation (promotes); invasion and metastasis (promotes); escaping immune response to cancer (suppresses)
Homologues: Orthologues: chimpanzee IL7R (99% identical), macaque IL7R (97% identical), dog IL7R (77% identical), pig IL7R (75% identical), rabbit IL7R (75% identical), guinea pig IL7R (70% identical), rat Il7r (66% identical), mouse Il7r (64% identical), tropical clawed frog il7r (24% identical). Paralogues in human: IL4R (15% identical), IL21R (14% identical), IL2RB (14% identical), IL9R (13% identical), CSF2RB (13% identical), EPOR (12% identical), MPL (10% identical).
Diseases named in the same sentence as IL7R in open-access papers:
IL7R is named in the same sentence as 358 diseases in open-access papers, as found by Europe PMC text mining. Sharing a sentence is not in itself a finding about the gene and the disease. The quoted sentences say what the papers report.
autoimmune disease (67 papers, 2009 to 2026). A disorder resulting from loss of function or tissue destruction of an organ or multiple organs, arising from humoral or cellular immune responses of the individual to their own tissue constituents. "Alternative exon 6 skipping of the interleukin 7 receptor (IL7R) gene results in the formation of soluble IL7R (sIL7R), and sIL7R expression is strongly associated with the development of autoimmune diseases such as multiple sclerosis (MS)." (PMID 40076889, 2025). "Reportedly, the interleukin-7 receptor (IL7R) is essential for the development and homeostasis of T cells, and its dysregulation has been associated with various autoimmune diseases and infections." (PMID 41332907, 2025). "Previous research has linked IL-7R polymorphisms to autoimmune diseases such as inflammatory bowel disease, systemic lupus erythematosus, and multiple sclerosis." (PMID 40642097, 2025). "These genes included IL2RG and IL32, which are linked to autoimmune diseases, and IL7R, which is the most prominent example of a risk allele-associated alternatively spliced gene in MS." (PMID 40943121, 2025). "Genetic polymorphisms in IL-7R, such as rs6897932, are associated with increased susceptibility to autoimmune diseases by affecting the expression of surface and soluble IL-7R in monocytes and T cells." (PMID 40313966, 2025). "Genetic variations in the IL-7 receptor (IL-7R) are also associated with the susceptibility to autoimmune diseases." (PMID 40313966, 2025). "Among the susceptibility regions for autoimmune diseases, we evaluated the polymorphisms of four genes (IL7R, CAPSL, CD226, and CLEC16A) and found the SNPs within two of these genes, IL7R and CAPSL, to be significantly associated with AITDs." (PMID 38612837, 2024). "Increased susceptibility to autoimmune diseases such as MS, type 1 diabetes or RA have been linked to several single nucleotide polymorphisms in IL-7R gene loci." (PMID 32849527, 2020). "Genetic polymorphisms at IL7R, the locus encoding the alpha chain of the IL-7 receptor, are associated with predisposition to several autoimmune diseases including Ankylosing Spondylitis, Multiple Sclerosis, and Primary Biliary Cirrhosis1–3." (PMID 31594933, 2019). "IL-7 is a key factor in T cell immunity and common variants at IL7R, encoding its receptor, are associated with autoimmune disease susceptibility." (PMID 31594933, 2019). "Four genes CTLA4, IL2RA, ICOS, and IL7R have been associated with a group of autoimmune diseases in GWAS and with autoimmunity in the HPO database." (PMID 31695696, 2019). "In this study, we investigated the impact of the single nucleotide polymorphism rs6897932 in the IL-7 receptor α-chain (IL-7Rα) which has previously been associated with several autoimmune diseases." (PMID 29456530, 2018). "IL-7/IL-7R signaling, which regulates lymphocyte growth and survival, has been implicated in the development of malignancies and autoimmune diseases." (PMID 28878234, 2017). "This notion was further supported by polymorphic analysis in human MS and SLE, in which polymorphisms of IL-7R were associated with the susceptibility to autoimmune diseases, such as SLE." (PMID 27069677, 2016). "It favor of the previous assumption are data indicating that dysregulation of the IL-7/IL-7R axis has long been implicated in autoimmune diseases, such as type 1 diabetes, multiple sclerosis and rheumatoid arthritis." (PMID 26448779, 2015). "IL7R is involved in enhancement of NK cell maturation and survival and is genetically associated with susceptibility to autoimmune diseases, especially multiple sclerosis." (PMID 22253695, 2012). "This is reflected in the raft of mutants and variants of IL-7R components and downstream signaling molecules that have been identified in the context of immunodeficiencies, autoimmune disorders and lymphoid malignancies, but also through the use of pathway modulators as therapeutics." (PMID 41750289, 2026).
autoimmune disease (continued). "Variants in IL7R have been linked to multiple autoimmune diseases, including AS." (PMID 39185422, 2024). "Genetic polymorphisms in IL7R are associated with susceptibility to various autoimmune diseases." (PMID 37373186, 2023). "IL7R deficiencies have been shown to contribute to autoimmune diseases such as SCID60." (PMID 30297856, 2018). "Strong and specific elimination of enhanced IL-7R-positive cells, as a common pathogenesis of both lymphoid malignancy and autoimmune disease, might prevent the development of malignancy or autoimmune disease in high-risk patients." (PMID 28878234, 2017). "Thus, IL7R polymorphisms have been studied in several infectious diseases and autoimmune diseases, showing a key role in the evolution of patients." (PMID 26123260, 2015). "The IL7R gene plays a key role in the development and function of the immune system, and mutations or abnormalities in the IL7R gene may be associated with the occurrence and development of a number of immune-related diseases, such as autoimmune diseases and immunodeficiency diseases." (PMID 40165301, 2025). "In addition, a functional IL7RA polymorphism (rs6897932) that interferes with IL-7R alternative splicing and thereby leads to reduced sIL-7R levels in plasma was found to be associated with autoimmune diseases and to affect immune reconstitution in AIDS patients." (PMID 28582466, 2017). "Given that the IL7R rs6897932 CC genotype is related to increased risk of autoimmune diseases, it is possible to speculate that higher level of sCD127 may confer worse immunological control of HCV infection in liver, with a higher necroinflammatory activity in liver biopsy." (PMID 26123260, 2015). "Given the well-established role of IL-7 in autoimmune processes, the utility of anti-IL-7R therapy has been explored in various autoimmune diseases, yielding promising preclinical study results." (PMID 40642097, 2025). "Aberrant expression of IL-7 and soluble IL-7Rα in plasma is indicative of pathological T cell immunity in chronic viral, inflammatory, and autoimmune diseases." (PMID 38408097, 2024). "IL7R (interleukin 7 receptor) is a heterodimeric complex composed of IL-7Rα and γ chains and is involved in autoimmune diseases such as IBD, RA, and MS." (PMID 38774864, 2024). "Stimulation of the receptor for Interleukin 7 (IL7R) has been shown to play an important role in the development and progression of autoimmune diseases." (PMID 38612837, 2024). "On the other hand, our results seem to discard the influence in AITDs susceptibility of rs3194051 for IL7R, rs763361 for CD226, and rs725613 for CLEC16A SNPs previously associated with other autoimmune diseases." (PMID 38612837, 2024). "IL-7 plays an important role in T-cell development, homeostasis, and immune tolerance, suggesting the use of the IL-7/IL-7Rα pathway as a target for autoimmune disease treatment." (PMID 37370001, 2023). "Anti-IL-7R neutralizing monoclonal antibodies have demonstrated therapeutic effect in preclinical research of autoimmune diseases, such as autoimmune diabetes and arthritis." (PMID 36142322, 2022). "IL-7R signal transduction play a crucial role in the advancement and progression of lymphoid malignancy and autoimmune diseases." (PMID 36142322, 2022). "IL-7Rα, and its signaling pathway, remains a potentially important target for both cancer and autoimmune diseases." (PMID 33755713, 2021). "There is increasing evidence which implicates aberrant IL-7/IL-7R signaling in the pathogenesis of numerous autoimmune diseases, such as rheumatoid arthritis, type I diabetes, MS, systemic lupus erythematosus and Primary Sjögren’s Syndrome." (PMID 33755713, 2021). "The interaction of these genes (IL7R, CD40 and LAG3) with MHC class molecules is associated with MS and other autoimmune diseases." (PMID 32111053, 2020).
autoimmune disease (continued). "The possibilities of ADCs in combination with IL-7R have previously been considered after confirming the involvement of IL-7 signaling in steroid-resistance when addressing the treatment of autoimmune diseases and cancers." (PMID 32849527, 2020). "The relevance of IL-2Rα and IL-7Rα regulation for development of autoimmune diseases including T1D has been clearly shown." (PMID 31110501, 2019). "Further refinement of this approach will be required to separate the beneficial from the adverse effects of anti-IL-7Rα antibodies to treat autoimmune disease." (PMID 30908554, 2019). "The common gamma chain (γc) contributes to the formation of different cytokine receptors [e.g., IL-2 receptor (IL-2R), IL-7R, and IL-15R], which are important for generation of self-reactive T-cells in autoimmune diseases, like in type 1 diabetes (T1D)." (PMID 31110501, 2019). "In agreement with this, blocking the IL-7R in experimental animal models ameliorated autoimmune disease manifestations." (PMID 29506153, 2018). "Aberrant expression of plasma IL-7 and soluble IL-7R are found in autoimmune diseases and chronic viral infections." (PMID 28582466, 2017). "In this respect, murine models of autoimmune diseases treated with inhibitors of IL-7/IL-7Rα signaling show preventive or therapeutic efficacy." (PMID 28356069, 2017). "Several lines of study have recently demonstrated that an increased level of soluble IL-7R (sIL-7R) had clinical implications in autoimmune diseases, including rheumatoid arthritis (RA), multiple sclerosis (MS), and SLE." (PMID 27069677, 2016). "Additionally, genomic variants in IL7R and CD226 have been associated with other autoimmune diseases, such as type 1 diabetes and rheumatoid arthritis." (PMID 40076709, 2025). "These include Il-7 and its receptor Il7R, CD226, CAPSL, and CLEC16A, which appear to be attractive candidates for further studies to explore the pathogenic mechanisms and potential therapeutic options for autoimmune diseases." (PMID 38612837, 2024). "Finally, we examined cis-pQTLs of the HLA-pGenes identified from the flagship pQTL study, and found that the cis-pQTLs of five HLA-pGenes—CD5, CD6, IL7R, SLAMF8, and TNFSF11—are themselves associated with autoimmune diseases with HLA risk." (PMID 39085222, 2024). "Exon 6 encodes for the transmembrane domain of IL7R; therefore, its inclusion leads to a transmembrane-bound isoform, while skipping of exon 6 results in a soluble isoform of IL7R (sIL7R), which is involved in the pathogenesis of an autoimmune disease called multiple sclerosis (MS)." (PMID 37511171, 2023). "Several anti-IL-7Rα blocking mAbs are currently in Phase I or Phase IIa trials in patients with autoimmune diseases where IL-7R seems to play a critical role, such as type 1 diabetes and multiple sclerosis, or Sjogren’s syndrome and inflammatory bowel disease, respectively." (PMID 33081391, 2020). "Finally, it is relevant to note here that anti-IL-7Rα mAbs are being tested in the clinic for autoimmune diseases (NCT01808482, NCT03239600, NCT01740609, NCT02045732, NCT02038764)." (PMID 30908554, 2019). "Hence, while anti-IL-7Rα mAb treatment demonstrated preclinical efficacy, preventing relapse in patients suffering from chronic inflammatory and/or autoimmune diseases will probably require iterative administrations." (PMID 30367166, 2018). "Consequently, treatment with an IL-7Rα-blocking antibody significantly reduced autoimmune disease manifestations in this model." (PMID 22102903, 2011). "IL-7, a member of the IL-2 family, is considered to affect aberrant immune activity in autoimmune diseases, such as diabetes and multiple sclerosis, and chronic inflammatory diseases, such as rheumatoid arthritis, ankylosing spondylitis, and inflammatory bowel disease, by binding to IL-7R." (PMID 40240976, 2025). "Furthermore, recent studies suggest that effects on the IL7/IL7R pathway may be important in the treatment of autoimmune diseases." (PMID 38612837, 2024).
autoimmune disease (continued). "Targeting of IL-7:IL-7Rα for therapeutic development in autoimmune diseases has mainly focused on the development of monoclonal anti-IL-7Rα antibodies which could be beneficial by blocking IL-7Rα and subsequently attenuating the action of effector T cells but retaining the Treg activity." (PMID 32849527, 2020). "Nevertheless, recent studies suggest that immunosuppression induced by treatment of mouse autoimmune arthritis with an anti-IL-7Rα ADC could be well tolerated clinically for a period of time, and very promising results have been reported from anti-IL-7R mAb clinical trials for autoimmune diseases." (PMID 33081391, 2020). "Thus, IL-7R targeting, perhaps through mAbs, might be a means of treating both lymphoid malignancies and autoimmune diseases." (PMID 28878234, 2017). "Therefore, the potent steroid-resistance of IL-7R-positive cells might be a common feature of both normal conditions and the pathological conditions of lymphoid malignancy and autoimmune disease." (PMID 28878234, 2017). "GSK2618960 is a humanized IgG1 monoclonal antibody directed against the alpha component (IL-7Rα; CD127) of TSLPR and is being developed for the treatment of autoimmune diseases (including multiple sclerosis)." (PMID 35572064, 2022). "Of 223 hypomethylated regions identified, several were in promoters of autoimmune disease GWAS loci (ARID5B, CD69, HDAC9, IL7R, TNIP1 and TRAF1)." (PMID 32231389, 2020). "Therefore, skewing IL-7Rα/PD-1 balance towards PD-1 by either stimulating PD-1/PD-L1 pathway or suppressing IL-7Rα signaling may have therapeutic potential for the treatment of autoimmune diseases, including MS." (PMID 27912762, 2016). "Considering that autoimmune disease pathogenesis invariably involves the participation of CD4+ T cells, it is likely that blockade of IL-7Rα signaling will be an efficient treatment in a wide spectrum of autoimmune and inflammatory disorders." (PMID 22102903, 2011). "Genome-wide association studies (GWASs) have also identified several non-HLA genetic variants linked to MS, including those in the interleukin-7 receptor (IL7RA), interleukin-2 receptor (IL2RA), CD58, and CLEC16A genes, indicating a shared genetic foundation with other autoimmune diseases." (PMID 40724862, 2025). "Psoriasis is an autoimmune disorder for which the contribution of the IL-7/IL-7Rα signalling pathway has not been investigated to date." (PMID 31406267, 2019). "In women with long-term type 1 diabetes and an associated autoimmune disease, there was an increase in CD69 expression and a decrease in the survival B-cell lymphoma 2 (BCL-2) (p < 0.05) and CD127 (IL-7R) (p < 0.01) marker expression compared with women without a concomitant autoimmune disorder." (PMID 34350463, 2021). "The notion that low IL7R expression levels are beneficial for reaching old age healthily corresponds with previous observations that autoimmune disease patients express increased levels of the IL receptor/ligand complex genes and that antagonizing IL7 or IL7R may offer possible treatment." (PMID 26566388, 2015). "As A7R-ADC treatment appeared to eliminate IL-7R-positive cells strongly and specifically, we hypothesized that A7R-ADC might have distinctive immunosuppressive activity that could be effective against various autoimmune diseases, particularly in steroid-resistant conditions." (PMID 28878234, 2017).